IRF4 (interferon regulatory factor 4)
Diseases named in the same sentence as IRF4 in open-access papers (continued):
Sharing a sentence is not in itself a finding about the gene and the disease.
Stroke (continued). "Integrative transcriptional and cell survival analyses showed that IRF4 functions mechanistically as a transcription activator of serum response factor (SRF) crucial to salvage neurons during stroke." (PMID 24510125, 2014). "Mechanistically, we demonstrated that following stroke, IRF4 binds to the promoter region of SRF, thereby initiating SRF transcription." (PMID 24510125, 2014). "The present study elucidated a neuronal role of IRF4 in which IRF4 is both sufficient and necessary for neuronal survival in experimental stroke." (PMID 24510125, 2014). "Taken together, these data demonstrated that neuronal IRF4 provides cerebroprotection against stroke insults." (PMID 24510125, 2014). "In the present study, we for the first time depicted IRF4 as a critical neuroprotective regulator during stroke." (PMID 24510125, 2014). "We hypothesized that Kdm6a/5c demethylate H3K27Me3/H3K4Me3 in microglia respectively, and mediate the transcription of interferon regulatory factor 5 (IRF5) and IRF4, leading to microglial pro-inflammatory responses and exacerbated stroke injury." (PMID 39399684, 2024). "Notably, animals with conditional deletion of the IRF5 and IRF4 genes in microglia following stroke showed clear behavioral changes." (PMID 39649720, 2024). "Lastly, we evaluated stroke outcomes in these IRF5 or IRF4 CKO aged mice." (PMID 35963621, 2022). "In addition, increased IRF4 expression was reported to quench pro-neuroinflammatory responses and improve stroke outcomes, suggesting that the function of IRF4 is modified under different conditions." (PMID 36567333, 2022). "IL-1β/IL-6 increased but IL-12p40 decreased in IRF4 CKO vs. flox mice after stroke." (PMID 35963621, 2022). "We found aged microglia express more IRF5 and less IRF4 compared to young microglia after stroke." (PMID 35963621, 2022). "Contrary to this pattern, microglial IRF4 MFI in young mice was significantly higher than in aged mice in either the sham or the stroke groups; in addition, young microglial IRF4 significantly increased after stroke, an ischemic effect that was not seen in the aged cohort." (PMID 35963621, 2022). "Nevertheless, the role of IRF4 on neonatal stroke remains unknown, and thus was explored as a downstream signaling molecule of KLF2 in neonatal hypoxic-ischemic brain injury in our study." (PMID 35091544, 2022). "Moreover, in a murine model of experimental stroke, IRF4+ conventional type 2 DCs rapidly infiltrated into the ischemic brain and became the major source of IL-23, followed by IL-17-dependent secondary tissue damage." (PMID 32456211, 2020). "Hence, an investigation into the mechanism of the post-stroke induction of IRF4 is required in future studies." (PMID 24510125, 2014). "To investigate whether IRF4 is involved in ischaemic stroke, we tested IRF4 expression in an established stroke mouse model using left middle cerebral occlusion (MCAO) for 45 min, followed by reperfusion ceded at the indicated time points." (PMID 24510125, 2014). "In this study, we evaluated the neuronal effect of IRF4 in a stroke model." (PMID 24510125, 2014). "In addition, IRF4 possesses the ability to regulate neuroinflammation and influence stroke outcome." (PMID 35091544, 2022). "In the present study, we hypothesized IRF4 CKO worsens while IRF5 CKO improves stroke outcomes." (PMID 35963621, 2022). "Interestingly, the mRNA level of IRF4 exhibited biphasic increases after stroke." (PMID 29131464, 2018). "Thus, we speculated that in response to stroke, IRF4 upregulates SRF to counteract programmed neuronal death." (PMID 24510125, 2014). "Interestingly, we observed significant upregulation of IRF4 upon stroke insults." (PMID 24510125, 2014). "Studies have shown that IRF5 and IRF4 correspond to pro-inflammatory and anti-inflammatory features in microglia after stroke, and IRF5-IRF4 signals form a regulatory axis to balance pro-inflammatory and anti-inflammatory activation in microglia." (PMID 41301548, 2025).
Stroke (continued). "The pro-inflammatory (TNF-α, IL-1β, IL-6, IL-12 p40, and MIP-1α), and the anti-inflammatory (IL-4 and IL-10) mediators were examined by ELISA in IRF5 or IRF4 CKO aged mice plasma, 3 days after stroke." (PMID 35963621, 2022). "Since microglial activation triggers and perpetuates immune responses to stroke and IRF5/IRF4 signaling regulate microglial activation, we next wanted to know if microglial IRF5 or IRF4 signaling impacts on plasma cytokine levels." (PMID 35963621, 2022). "Stroke effects on these IRFs’ expression were also age-dependent, as in aged microglia only IRF5 expression increased after stroke in contrast to IRF4 that only increased in young ischemic microglia." (PMID 35963621, 2022). "Our previous studies have found IRF5 and IRF4 signaling also regulate microglial activation in neonatal and young adult mice after stroke, with IRF5 being pro-inflammatory and IRF4 anti-inflammatory." (PMID 35963621, 2022). "IRF4 and IRF5 form a regulatory axis that is critical for microglial polarization and immune responses to stroke." (PMID 33712031, 2021). "Consequently, pharmacological reagents could be developed to reduce IRF5 or increase IRF4 expression in microglia after stroke, so that the pro-inflammatory response can be prevented and the anti-inflammatory response trigger earlier to clear the ischemic detriment and boost the tissue repair." (PMID 33317034, 2020). "For example: Microglial IRF5 CKO mice and microglial IRF4 CKO mice directly alter the activation phenotype of microglia, leading to corresponding changes in inflammatory responses, which in turn affect the prognosis of stroke." (PMID 39649720, 2024). "Our flow data showed IRF5 was significantly expressed in aged vs. young microglia after stroke, as opposed to IRF4 that demonstrated an opposite expression pattern in microglia of the two ages." (PMID 35963621, 2022). "To investigate whether IRF5 and IRF4 signaling induce similar inflammatory responses to stroke in aged microglia as that in the young, we examined both surface and intracellular inflammatory markers in microglia from IRF5 or IRF4 CKO aged mice at 3d of MCAO." (PMID 35963621, 2022). "Our data showed IRF4 or IRF5 had muted function either in the expression of some aged microglial cytokines or in phagocytosis; however, they both impacted on stroke outcomes in a similar pattern as that in young mice." (PMID 35963621, 2022). "Among all IRFs, only IRF4 and IRF5 showed sex-specific expression in aged mice brains after stroke." (PMID 33712031, 2021). "By using the aged IRF4/IRF5 microglial CKO mouse models, the study aimed to selectively suppress microglial pro-inflammatory activation and promote its anti-inflammatory response, and will potentially help develop new, effective therapeutic strategies against stroke." (PMID 35963621, 2022). "Excitingly, our data have indeed confirmed these effects: H3K4me1 and H3K27me1 bind to more IRF4/5 DNA, respectively, in female vs. male microglia after OGD; however, mice with two copies of X have higher IRF5 and lower IRF4 level compared to one X mice after stroke." (PMID 33712031, 2021). "Likewise, in murine stroke models, where IRF4 promotes neuronal survival, Irf4 expression did not peak until 72 h after ischemia induction." (PMID 31632388, 2019). "Whether IRF5 and IRF4 also mediate microglial activation after stroke is not known." (PMID 29131464, 2018). "Nevertheless, the age-dependent expression of the two IRFs was not translated into an age-dependent role of the IRF5-IRF4 axis, as IRF5 CKO induced a beneficial and IRF4 CKO elicited a detrimental effect on stroke outcomes, similar to what we have seen in young and neonatal mice stroke models." (PMID 35963621, 2022). "While models of microglial IRF5 and IRF4 CKO mice are particularly helpful in examining the transition between microglial activation states, they might not accurately replicate the intricacy of a real stroke." (PMID 39649720, 2024).
Autoimmunity (18 papers, 2010 to 2025). The occurrence of an immune reaction against the organism's own cells or tissues. "Specifically, mice with IRF4-deficient Tregs show multi-organ autoimmunity mediated by uncontrolled Th2 immune responses." (PMID 34631704, 2021). "Initial studies demonstrated that mice with Treg-specific deficiency in IRF4, a transcription factor that is necessary for Th2 differentiation, developed uncontrolled Th2-mediated autoimmunity." (PMID 34631704, 2021). "Treg-specific Irf4-deficient mice develop multi-organ autoimmunity, exhibiting profound Th2 responses." (PMID 30559442, 2018). "Treg-cell restricted Irf4 inactivation results in autoimmunity due to impaired eTreg-cell formation but also delayed tumor growth as consequence of reduced accumulation of eTreg cells in tumors." (PMID 40726986, 2025). "JunB facilitates the binding of IRF4 to a subset of its transcriptional target sites, like CTLA4 and ICOS, and Treg-specific deficiency in JunB results in multiorgan autoimmunity." (PMID 34631704, 2021). "Various genetic and functional studies have also pointed to IRF4 as a master regulator for autoimmunity." (PMID 32346613, 2020). "Although autoimmunity in DKO mice is accompanied by dysregulated IRF4 activity in both T and B cells, SWAP-70 is also known to regulate multiple aspects of DC biology leading us to directly evaluate DC development and function in these mice." (PMID 26544714, 2015). "Furthermore, impaired stability of IRF4 in Treg cells due to a defect in protein SUMOylation results in development of autoimmunity." (PMID 40726986, 2025). "We have also shed light on the mechanisms by which USP7 controls IRF4 and IRF8 expression in cDCs in the context of autoimmunity." (PMID 40247205, 2025). "In another study, it was demonstrated that the inappropriate phosphorylation of IRF4 by ROCK2 downregulated production of IL-17 and IL-21 cytokines, which aggravated autoimmunity in mouse models." (PMID 38674328, 2024). "A recent study has demonstrated that interferon regulatory factor 4 (IRF4), a transcription factor regulating IL-17 and IL-21 production, is involved in autoimmunity development." (PMID 33805933, 2021). "Our observations further highlight the fundamental role of Ezh2 in regulating IRF4 and IRF8 in tolerogenic DCs and limiting autoimmunity." (PMID 32899608, 2020). "All these lines of evidence point to IRF4 as a relevant player for IRGs activation and thus, IFN signature in autoimmunity." (PMID 30666255, 2018). "IRF4 is expressed in dendritic cells, monocytes/macrophages, granulocytes and B-cells, all cell subsets relevant for IFN signature in autoimmunity." (PMID 30666255, 2018). "Of note, IRF4, MEF2C, and SPI1 have been reported to be crucial in the development of autoimmunity." (PMID 35350715, 2022). "The findings herein presented shed new light into the clinical value of this complex regulation between IRF4 and IRGs in autoimmune patients and prove this field worthy of further research in order to better delineate the effect of IRFs on the IFN signature(s) in autoimmunity." (PMID 30666255, 2018). "The distinct, mutual expression patterns related to IRF4 and IRGs expression in SLE and RA patients support the concept that IRFs could play a role in the regulation and editing of the type I IFN signature in autoimmunity." (PMID 30666255, 2018). "Moreover, inactivation of MITF in mice induced spontaneous B cell activation and autoantibody production by suppressing interferon regulatory transcription factor (IRF)-4, which suggested a role of MITF in maintaining B cell immune tolerance and prevention of autoimmunity." (PMID 21170274, 2010).
leukemia (18 papers, 2011 to 2024). A malignant (clonal) hematologic disorder, involving hematopoietic stem cells and characterized by the presence of primitive or atypical myeloid or lymphoid cells in the bone marrow and the blood. "Some were already associated with T-CD8+ leukemias (Il2ra; and Pdgfrb) and others were associated with other types of T-leukemias or cancer (Irf4, Hrb, Depdc6, Als2cl, Tle4 and Cdc42ep3), thus validating our approach." (PMID 23902727, 2013). "Moreover, MYC-induced leukemia was greatly accelerated in IRF4 ± deficient mice showing hyperproliferative large leukemic pre-B cells resistant to apoptosis." (PMID 36495369, 2023). "In addition to mice mutated in Pax5 or Ikzf1, Irf4/Irf8−/−, and Irf4/Spi1−/− mice have been shown to develop leukemia early in life at a high incidence." (PMID 35459909, 2022). "Our aim was to investigate the expression levels of IRF4 in the diagnostic samples of pediatric leukemias and compare them to those of healthy controls, in order to determine aberrant gene expression and whether it extends to leukemic subtypes other than the relatively mature ALL subpopulation." (PMID 23977280, 2013). "Next, we compared Irf4−/− leukemia to the complex landscape of human BCP-ALL subtypes, using a published human BCP-ALL cohort for which a random forest classifier had been established." (PMID 35459909, 2022). "Due to the known impaired maturation of Irf4−/− preB cells, spontaneous eruption of preB-leukemia seemed plausible: In spleen sections, infiltrating cells stained positive for both B220 and Igμ (although less than untransformed “follicle” B cells) and Ki67." (PMID 35459909, 2022). "Phenotypically, Irf4−/− cells accumulated at the fr.C stage and expressed surface λ5; exactly like Irf4−/− leukemia." (PMID 35459909, 2022). "Furthermore, the IRF4 levels were related to leukemic transformation and a shorter leukemia-free survival; moreover, the risk of myelofibrosis transformation in polycythemia vera and essential thrombocythemia patients was more frequent in cases with lower IRF4 levels." (PMID 34952638, 2021). "In summary, IRF4+/−Myc mice develop pre-B cells derived leukemia that is transplantable in the syngenic mice." (PMID 21818355, 2011). "In this report, we show that c-Myc induced leukemia was greatly accelerated in the IRF4 heterozygous mutant mice." (PMID 21818355, 2011). "Collectively, our results indicate that the IRF4+/−Myc mice developed leukemia that originated from B cell progenitors." (PMID 21818355, 2011). "Our results show that c-Myc induced leukemia was greatly accelerated in the IRF4 heterozygous mice (IRF4+/−Myc); the average age of mortality in the IRF4+/−Myc mice was only 7 to 8 weeks but was 20 weeks in the control mice." (PMID 21818355, 2011). "All ten recipient mice developed leukemia similar to IRF4+/−Myc mice and died within two month of transplantation." (PMID 21818355, 2011). "The finding that c-Myc induced leukemia was dramatically accelerated in the IRF4+/− mice indicates that IRF4 functions as a tumor suppressor in c-Myc induced leukemia." (PMID 21818355, 2011). "As overt leukemia is characterized by systemic presence, we tested whether already preleukemic Irf4−/− B-cell progenitors would leak from the BM." (PMID 35459909, 2022). "Irf4 deficiency is not by itself associated with an increased risk of leukemia, but cooperates with oncogenes to promote leukemogenesis." (PMID 28692033, 2017). "Whereas a marginally significant correlation appeared to exist between abnormal IRF4 expression and estimated leukemia-free time (p = 0.08 and p = 0.05), a significant correlation appeared (p = 0.03) when leukemia-free time was estimated within a specific time frame of 3 years." (PMID 23977280, 2013). "Again, our results are in contrast to other studies documenting a down-regulated IRF4 expression in adult myeloid leukemias, even though this is most probably due to age-related dissimilarities and a different pathogenetic leukemia mechanism." (PMID 23977280, 2013).
leukemia (continued). "This might suggest that there is a dose-dependency of childhood leukemia for ectopically expressed IRF4, a characteristic that could be explored further for its therapeutic potential." (PMID 23977280, 2013). "Finally, we investigate the prognostic impact of high IRF4 expression in the clinical course of childhood leukemia, through possible correlations with minimal residual disease (MRD) and survival outcome." (PMID 23977280, 2013). "In addition, a statistically significant correlation was found between high IRF4 expression and relapse, suggesting a prognostic value of IRF4 in the clinical course of childhood leukemias." (PMID 23977280, 2013). "Here, we report that IRF4 suppresses c-Myc induced leukemia in EμMyc mice." (PMID 21818355, 2011). "Our results show that c-Myc induced leukemia was dramatically accelerated in IRF4+/−Myc mice." (PMID 21818355, 2011). "Therefore, fully transformed leukemia remained targetable by IRF4 re-expression." (PMID 35459909, 2022). "Our results show that ectopic expression of IRF4 follows the reverse expression pattern of what is encountered in normal B-cell development and that there might be a dose-dependency of childhood leukemia for aberrantly expressed IRF4, a characteristic that could be explored therapeutically." (PMID 23977280, 2013). "A total of 100 TFs with silenced promoters were downregulated relative to AML, including hematopoietic regulators and genes known to be involved in leukemia, such as CEBPA, CEBPD, KLF4, IRF4 or MEIS1." (PMID 38972954, 2024). "Correspondingly, shRNA-mediated knockdown of IRF4 counteracted exhaustion, inhibited T cell differentiation, improved CAR T cell cytotoxicity, and augmented CAR T cell performance in leukemia bearing mice." (PMID 37287982, 2023). "Herein, we report that adult Irf4−/− mice spontaneously develop BCP-ALL with age and delineate the steps from disturbed Irf4−/− B lymphopoiesis to overt leukemia." (PMID 35459909, 2022). "As Irf4 deletion was a prerequisite for leukemia in our model, we examined the effect of forced IRF4 re-expression, using RVs coding for GFP alone (EV-RV) or plus IRF4 (IRF4-RV)." (PMID 35459909, 2022). "Interestingly, when leukemia-free time was estimated within a specific time frame of 3-years (i.e. only the patients diagnosed in the years 2008, 2009 and 2010 were included in the analysis), a significant correlation appeared to exist between high IRF4 expression and relapse (p = 0.03)." (PMID 23977280, 2013). "In contrast, our results show that IRF4 behaves like a classical tumor suppressor, downstream of pre-BCR signaling, that functions to inhibit c-Myc induced leukemia." (PMID 21818355, 2011). "Therefore, we compared Aicda expression in sorted Irf4−/− and wt fr.A-D cells to that of wt mesenteric (m)LN- and CD4+ TH1-cells as controls and to individual leukemia samples." (PMID 35459909, 2022). "Since all of these except Ph-like are defined by specific gene rearrangements, that we had not detected in Irf4−/− mouse leukemia, we excluded them as comparable candidates." (PMID 35459909, 2022). "Furthermore, the oncomir microRNA-125b is up-regulated in several types of leukemias, including acute myeloid leukemia (AML) and B-ALL and is reported to inhibit IRF4 expression while inducing tumorigenesis in hematopoietic progenitor cells and myeloid and B cell neoplasms." (PMID 36495369, 2023). "Interestingly, we show that childhood leukemia, irrespective of subtype or cell maturation stage, is characterised by a minimum of approximately twice the amount of IRF4 gene expression encountered in healthy children." (PMID 23977280, 2013).